SNAI2 (snail family transcriptional repressor 2)
Diseases named in the same sentence as SNAI2 in open-access papers (continued):
Sharing a sentence is not in itself a finding about the gene and the disease.
gastric cancer (18 papers, 2007 to 2025). A primary or metastatic malignant neoplasm involving the stomach. "SNAI2, a critical regulator of EMT, has been implicated in promoting EMT in gastric cancer by upregulating COL5A2 expression." (PMID 38872418, 2024). "FZD5, ELF3, TEAD1 and SNAI2 expression in 55 gastric cancer tissues was detected by immunohistochemistry." (PMID 33618713, 2021). "•TWIST1 and SNAI2 were validated as key regulators of THY1 in gastric cancer." (PMID 40476057, 2025). "In a previous study it was shown that LINC00261 could bind to SNAI2 and promote its degradation in gastric cancer." (PMID 32414223, 2020). "In this study, we systematically delineated the transcriptional regulatory landscape of THY1 in gastric cancer by identifying six robust putative regulators—PRRX1, TWIST1, SNAI2, MEIS3, VENTX, and EGR2—through an integrative multicohort approach." (PMID 40476057, 2025). "The results showed that EMT‐promoting factors SNAI1 and SNAI2 were significantly downregulated, while EMT repressors GRHL2 and OVOL1 were significantly upregulated, suggesting that zyxin negatively regulates EMT in gastric cancer cells." (PMID 37667739, 2023). "Interrogation of CCLE database revealed that FZD5 is positively correlated with epithelial-related factors CDH1 (E-cadherin), OCLN (Occludin), EPCAM and ELF3, while negatively correlated with mesenchymal-related factors VIM (Vimentin), SNAI2 (Slug), ZEB1 and ZEB2 in 37 gastric cancer cell lines." (PMID 33618713, 2021). "Together, these findings provide experimental evidence supporting TWIST1 and SNAI2 as direct regulators of THY1, integrating bioinformatic predictions and experimental insights into a cohesive model of THY1 transcriptional regulation in the context of gastric cancer." (PMID 40476057, 2025).
lung adenocarcinoma (18 papers, 2015 to 2024). A carcinoma that arises from the lung and is characterized by the presence of malignant glandular epithelial cells. "It has been reported to upregulate EMT-transcription factors like Snai1 and Snai2 in breast and lung adenocarcinoma." (PMID 37025658, 2023). "To validate the presence of differential expression between SNAI1 and SNAI2 in other cancers, we subjected the lung adenocarcinoma cell line, A549 to TGFβ treatment." (PMID 31165775, 2019).
cervical carcinoma (16 papers, 2016 to 2025). A carcinoma arising from either the exocervical squamous epithelium or the endocervical glandular epithelium. "The results of the RNA sequence in Snai2-overexpressing cervical cancer cells implied a strong correlation between Snai2 and TRIM31 with ubiquitin ligase activity." (PMID 40919166, 2025). "Snai2 is a transcription factor that inhibits the proliferation of cervical cancer cells and tumor growth." (PMID 40919166, 2025). "Snai2 was found to inhibit the Wnt/β-catenin signaling pathway in cervical cancer in our previous studies." (PMID 40919166, 2025). "All of these data indicated that overexpression of SNAI2 in cervical cancer cells attenuated the stem-like phenotype." (PMID 36674577, 2023). "In this study, by exogenously expressing SNAI2 in SiHa cells, SNAI2 exhibited the capacity to inhibit a stem-like phenotype in cervical cancer cells." (PMID 36674577, 2023). "In this study, SNAI2 exhibited a capacity for inhibition of the stem-like phenotype in cervical cancer cell lines." (PMID 36674577, 2023). "First, the protein levels of β-catenin and the Wnt/β-catenin signaling pathway target genes c-Myc and SOX2 were detected in SNAI2-modified cervical cancer cells." (PMID 36674577, 2023). "Our previous study demonstrated that SNAI2 attenuated the activity of the Wnt/β-catenin signaling pathway in cervical cancer cells." (PMID 36674577, 2023). "In our previous study, SNAI2 exhibited a capacity to inhibit cell growth and tumor formation in cervical cancer cells." (PMID 36674577, 2023). "In our previous study, SNAI2 exhibited the capacity to act as a transcriptional repressor of EPCAM in cervical cancer." (PMID 36674577, 2023). "In our previous study, SNAI2 exhibited an inhibitory effect on tumor formation in cervical cancer in a tumor-bearing model in nude mice." (PMID 36674577, 2023). "A de–regulation of Wnt signaling was also reported for liver and cervical cancer, associated with a reduction of EMT markers such as SNAI1, SNAI2, ZEB1 or VIM in cervical cancer–derived cell lines." (PMID 34062997, 2021). "Slug (Snai2) has been demonstrated to act as an oncogene or tumor suppressor in different human cancers, but the function of Slug in cervical cancer remains poorly understood." (PMID 27036045, 2016). "All of these results demonstrated that SNAI2 could attenuate the stem-like phenotype in cervical cancer cells through the EPCAM/β-catenin axis." (PMID 36674577, 2023). "In this study, SNAI2 exhibited the capacity to inhibit a stem-like phenotype in cervical cancer." (PMID 36674577, 2023). "EPCAM is considered a multifunctional transmembrane protein involved in the regulation of cell stemness and is required for stem cell survival or proliferation, and the inhibitory role of SNAI2 on trans-suppressing EPCAM expression in cervical cancer was reported in our previous study." (PMID 36674577, 2023). "As a result, miR-let-7c-5p/insulin-like growth factor 1 receptor/phosphatidylinositol-3 kinase/AKT serine/threonine kinase 1 (miR-let-7c-5p/IGF-1R/PI3K/AKT) and beta-catenin/snail family transcriptional repressor 2 (β-catenin/SLUG) were highlighted as potential targets against cervical cancer." (PMID 37576994, 2023). "In order to explore whether the alteration of EPCAM under SNAI2-overexpressing cells was involved in SNAI2 mediating the stemness of cervical cancer cells, EPCAMhigh and EPCAMlow cells were sorted by FACS from SiHa-SNAI2 cells, and then cultured to generate tumorspheres." (PMID 36674577, 2023). "However, the potential role of SNAI2 in regulating the stem-like phenotype in cervical cancer cells is still unknown." (PMID 36674577, 2023). "Our previous study revealed that Snai2 was able to inhibit tumors with high EPCAM expression and decrease the stem-cell-like properties of cervical cancer cells." (PMID 40919166, 2025).
cervical carcinoma (continued). "In our previous study, SNAI2 exhibited the capacity to inhibit cell proliferation, and promote cell motility and distant metastasis by trans-suppressing EPCAM expression in cervical cancer." (PMID 36674577, 2023). "The effect was less prominent in cervical cancer HeLa cells—we observed SNAI1/SNAI2 upregulation (though not so prominent as in A549 cells) in HeLa cells overexpressing HSAT2 without significant changes in cell morphology." (PMID 37108080, 2023). "All of these results suggested that SNAI2 blocked the nuclear translocation of β-catenin by inhibiting EPCAM expression, further suppressing the expression of c-Myc and SOX2, and ultimately attenuating the stem-like phenotype in cervical cancer cells." (PMID 36674577, 2023). "Our previous study demonstrated that SNAI2 could inhibit EPCAM expression by recognizing and directly binding the E-box motifs (CANNTG) in the proximal promoter region of EPCAM in cervical cancer cells, further inhibiting cell proliferation, and inducing EMT." (PMID 36674577, 2023). "Thus, in cervical cancer, there is a potential connection between SNAI2 trans-suppression of EPCAM expression and SNAI2-mediated inhibition of the stem-like phenotype." (PMID 36674577, 2023). "Therefore, the central question is whether there is a potential interaction mechanism between SNAI2 and EPCAM in regulating the stem-like phenotype in cervical cancer cells." (PMID 36674577, 2023). "In conclusion, this study reveals a negative relationship between SNAI2 and EPCAM in cervical cancer." (PMID 36674577, 2023). "In addition, the results of TMA (tissue microarray) also confirmed the negative correlation of SNAI2 and EPCAM protein level in cervical cancer tissues." (PMID 36674577, 2023).
bladder cancer (14 papers, 2014 to 2026). "Bulk RNAseq analysis revealed that A485 commonly downregulated SNAI2-related signaling pathways across multiple bladder cancer cell lines." (PMID 42258462, 2026). "In bladder cancer, SNAI2 mediated EMT has been reported to be critical for androgen-dependent metastasis." (PMID 29552304, 2018). "Indeed, overexpression of SNAI2 enhanced the migratory capacity of bladder cancer cells via Transwell assay." (PMID 42258462, 2026). "In particular, PHB-driven Wnt/β-catenin signaling and the Snai2–NADSYN1–PHB pathway have been shown to promote migration, invasion, and adverse phenotypes in bladder cancer models." (PMID 41154349, 2025). "In bladder cancer, SNAI1, SNAI2 and TWIST are differentially expressed and TWIST and SNAI2 expression have been shown to play an important role in tumor progression and metastasis formation." (PMID 25247809, 2014). "Collectively, our findings demonstrate that EP300 promoted bladder cancer cell migration via up-regulating SNAI2, targeting EP300 could be a potential therapeutic strategy to inhibit the process of bladder cancer invasion." (PMID 42258462, 2026). "For comparison, we included the atypical TPM bladder cancer cell line SCaBER, which expressed SNAI2, but not other mesenchymal markers tested." (PMID 40560846, 2025). "Correlation analysis in bladder cancer samples from TCGA BLCA demonstrated a positive correlation between mRNA levels of IGF2BP3 and SNAI1 (Snail), SNAI2 (Slug), CDH2 (N-cadherin), VIM (vimentin), and MMP9, further supporting the association between IGF2BP3 and EMT-related markers." (PMID 38504159, 2024). "Since knockdown of ITGAV and to a lesser extent treatment with the GLPG0187 compound in UM-UC-3 and RT-4 cells resulted in a significant decrease in SNAI2, SNAI2 might play an important role in EMT in bladder cancer." (PMID 25247809, 2014). "However, the protein expression of only SNAI2 (slug) was detected, suggesting that slug might be the main TF affecting EMT in bladder cancer." (PMID 30914736, 2019).
metastatic disease (13 papers, 2015 to 2025). "Among the metastatic tumors, significantly higher levels of SNAI2 were associated with higher Gleason grade (Gleason Score = 9) and lethality." (PMID 34792282, 2022). "However, the hallmark of metastatic tumors is highly invasive with slow proliferation, supported by activation of SNAI2." (PMID 34792282, 2022). "Intriguingly, in the MSKCC cohorts, a relatively higher level of SNAI2 was observed in distant metastatic tumors than in lymph node metastases." (PMID 34792282, 2022). "We found seven DEGs (CCND1, EGFR, ENTPD5, HOXA10, IGF1R, MYC, and SNAI2) related to metastatic disease." (PMID 35806108, 2022). "In patients with metastatic disease, increasing levels of TWIST protein are associated with cancer-caused death, and higher levels of SLUG (SNAI2) protein are present in cases with higher tumour grades." (PMID 30189837, 2018). "None of the available clinicopathological characteristics of either primary or metastatic tumors correlated significantly with SNAI2 levels." (PMID 29921289, 2018). "These conclusions strongly identify the SNAI2 gene as a key target for modern strategies to prevent or cure the metastatic disease." (PMID 25686823, 2015). "However, metastatic tumors are characterized by high invasiveness and slow cellular proliferation, supported by the activation of SNAI2." (PMID 36915125, 2023). "Methylation of SNAI2 was detected not only in primary tumors but also in metastatic tumors." (PMID 34792282, 2022). "Together, these results show that methylation of SNAI2 contributes to decreased SNAI2 expression, and reactivating SNAI2 may be required for metastatic tumor progression." (PMID 34792282, 2022). "After experimental validation of the association between the lower values of SNAI2 and ADAM23 methylation and clinical features of aggressive BCs, these methylation profiles could improve the management of metastatic disease." (PMID 30189837, 2018). "To investigate why SNAI2 is silenced in PC, we applied GSEA to genes highly enriched for either low or high SNAI2 levels in both the TCGA (primary tumor) and SU2C (metastatic tumor) cohorts." (PMID 34792282, 2022). "RUNX2 gene expression showed negative correlation with SNAI2 genes in primary and metastatic tumors." (PMID 34792282, 2022). "Conversely we observed genes associated with aggressive metastatic disease and EMT (VIM, SPARC, ZEB1, SNAI2, CTSB) upregulated in lung populations compared to lymph nodes." (PMID 34579762, 2021).
osteosarcoma (13 papers, 2013 to 2023). A usually aggressive malignant bone-forming mesenchymal neoplasm, predominantly affecting adolescents and young adults. "Jude-PeCan portal confirmed that SNAI2 is highly expressed in RMS tumors and, especially, FN-RMS compared to other pediatric cancers with only osteosarcoma tumors expressing higher SNAI2." (PMID 33420019, 2021). "To gain a better understanding of SNAI2 and VDR regulation in osteosarcomas, we evaluated H3K27ac and H3K4me1 epigenetic alterations in a panel of highly metastatic and low metastatic human OS cell lines (GSE74230)." (PMID 37228489, 2023).
liver cancer (11 papers, 2015 to 2025). An epithelial or non-epithelial malignant neoplasm that arises from the liver. "MiR-630 can specifically target human SNAI2 (Snail 2) in suppressing epithelial to mesenchymal transition (EMT) in lung and liver cancer cells; however, its role in myofibroblast differentiation has not been previously shown." (PMID 29273797, 2017). "In addition, miR-203 downregulation has been described in various cancers including esophagus, cervix, prostate, breast, and liver cancer, and miR-203 inhibits cancerous invasion by targeting SNAI1, SNAI2, ZEB2, and VEGFA." (PMID 26882562, 2016). "Moreover, HBV infection has been considered as a driving force for EMT during liver cancer evolution, with remarkably elevated expressions of EMT markers including Snail Family Transcriptional Repressor 2 (SNAI2) and Twist Family BHLH Transcription Factor 1 (TWIST1) in infected liver organoids." (PMID 35541903, 2022).
neuroblastoma (11 papers, 2013 to 2024). Neuroblastoma (NB) is the most common solid, extracranial childhood tumor. "TRPM7 also maintains the stem cell features of neuroblastoma by regulating the expression of the Snail family transcriptional repressor 2 (SNAI2) transcription factor, which is involved in epithelial–mesenchymal transitions and has antiapoptotic activity." (PMID 35887116, 2022). "Neuroblastoma-specific mesenchymal transcriptional signature was also repressed after BAF disruption in neuroblastoma cells, involving the epigenetic repression of key regulators of the mesenchymal phenotype, such as SNAI2, CDH11, CDH2, LOXL2 and NOTCH2." (PMID 36057593, 2022). "Next, we detected that MOXD1, as well as the MES-associated PRRX1, SNAI2, and NOTCH2 genes were virtually restricted to the MES-like SH-EP cells by analyzing extracted RNA from five different conventional neuroblastoma cell lines." (PMID 38905335, 2024). "Moreover, SNAI2 drives EMT in neuroblastoma cells, and, reciprocally, SNAI2 knockdown increases the sensitivity to apoptosis-inducing compounds and impairs the metastatic potential of neuroblastoma cells in vitro and in vivo." (PMID 25797249, 2015). "Future studies will determine how alterations in cytoskeletal dynamics affect the expression of SNAI2, and whether TRPM7-driven SNAI2 expression contributes to neuroblastoma progenitor-like features." (PMID 25797249, 2015). "Hence, our results strongly suggest that TRPM7 maintains stem cell features of neuroblastoma cells by expression regulation of SNAI2." (PMID 25797249, 2015). "Moreover, microarray-based expression profiling on control and TRPM7 shRNA transduced neuroblastoma cells indicates that TRPM7 controls a developmental transcriptional program involving the transcription factor SNAI2." (PMID 25797249, 2015). "Moreover, the neuroblastoma mesenchymal transcriptional signature, repressed after BAF disruption, is determined by a specific super-enhancer configuration, and many of these genes (LOXL2, SNAI2, CDH11, ITGAV) are associated with chromatin repressive events." (PMID 36057593, 2022). "By maintaining progenitor-like features and controlling a developmental transcriptional program involving the transcription factor Snail family transcriptional repressor 2 (SNAI2), TRMP7 has been proposed to contribute to neuroblastoma progression." (PMID 38255793, 2024). "Indeed, we confirmed by quantitative RT-PCR that expression of SNAI2 was reduced upon TRPM7 knockdown in both SH-SY5Y and SH-EP2 neuroblastoma cells." (PMID 25797249, 2015). "Moreover, overexpression of TRPM7 in the SNAI2 negative N1E-115 mouse neuroblastoma cell line induced expression of SNAI2." (PMID 25797249, 2015).
thyroid cancer (11 papers, 2017 to 2023). "By immunohistochemistry several transcription factors implicated in EMT induction, such as SLUG (SNAI2), TWIST1 and ZEB1 are all up-regulated in ATC compared to normal thyroid and well-differentiated thyroid cancers and coordinately act to repress E-cadherin (CDH1) expression." (PMID 29383121, 2017). "One research revealed that SNAI2 was more expressed in ATC than in normal tissues and other thyroid cancers." (PMID 36530988, 2022). "We validated the downregulation of SNAI2, SOX4, and TGFBR2, three targets never investigated in thyroid cancer cells, and of HMGA2, a miR-2 04-5p target previously identified in the lab (unpublished results), in TPC-1 and BCPAP cells following miR-204-5p overexpression." (PMID 37445942, 2023).
non-small cell lung carcinoma (10 papers, 2015 to 2024). A group of at least three distinct histological types of lung cancer, including non-small cell squamous cell carcinoma, adenocarcinoma, and large cell carcinoma. "Aspirin inhibits the pro-invasive phenotype of non-small cell lung carcinoma cell lines through SNAI2 downregulation." (PMID 34638901, 2021). "MSI2 depletion significantly down-regulates EMT markers (TGF-β receptor 1, SMAD3, SNAI1 and SNAI2) to inhibit non-small cell lung cancer metastasis." (PMID 31952541, 2020). "In addition, FOSL2 could regulate the epithelial-mesenchymal transitions (EMT), invasion, and migration by transcriptional regulation of SNAI2 in non-small cell lung cancer." (PMID 39010083, 2024).
triple-negative breast carcinoma (9 papers, 2013 to 2025). An invasive breast carcinoma which is negative for expression of estrogen receptor (ER), progesterone receptor (PR), and human epidermal growth factor receptor 2 (HER2). "Since that CA9 knockdown halts MDA-MB-231 xenografts, the available data agree on the crucial role of the beta-catenin-dependent CA9 and SNAI2 mRNA stability and expression in the biology of basal-like/triple-negative breast cancer." (PMID 24260469, 2013). "This approach could be particularly effective in tumors characterized by high levels of EGFR and Snai2, such as triple-negative breast cancer." (PMID 29674627, 2018). "The IGF2BP3-mediated snail family transcriptional repressor 2 (SLUG) activates SOX2 transcription, contributing to the self-renewal of triple-negative breast cancer cells." (PMID 37554271, 2023). "In this study, we show that SNAI2, a mediator of EMT highly expressed in triple-negative breast cancer, is upregulated in endocrine-resistant cells, whereas other EMT-associated transcription factors, such as SNAI1/3, TWIST1/2, ZEB1/2, FOXC2, and GSC, are unaltered." (PMID 29921289, 2018).